OCLN (occludin)
Diseases named in the same sentence as OCLN in open-access papers (continued):
Sharing a sentence is not in itself a finding about the gene and the disease.
colitis (continued). "Additionally, intestinal barrier proteins ZO‐1 and Occludin were further decreased in the MitoBloCK‐6+DSS group, indicating that MitoBloCK‐6 exacerbated the impairment of intestinal barrier integrity in DSS‐induced colitis." (PMID 41098076, 2025). "In another study involving a bioactive compound, it could relieve dextran sodium sulfate-induced colitis in mice while preventing the negative morphological and functional effects on occludin and ZO-1." (PMID 40244215, 2025). "Specifically, the mRNA expression of intestinal barrier proteins (ZO-1, Claudin-1, Occludin and E-cadherin) were elevated, and the activities of antioxidant enzymes (GSH-Px, SOD) in the colon were increased, it exhibited a mitigating influence on the symptoms of colitis in mice." (PMID 41154565, 2025). "In addition, XSQ treatment restored the dysregulated gut microbiota in colitis mice, increased short chain fatty acids (SCFAs) and normalized the MAPK/ERK/JNK signaling pathways, promoted expression of tight junction protein Occludin, Claudin-1, and E-cadherin proteins." (PMID 39616288, 2024). "In addition, ALL could ameliorate the barrier damage in colitis, as indicated by changes in the ALL group in the levels of occludin and claudin-1 converging to the control group." (PMID 36831001, 2023). "A direct effect of infliximab on the expression of the tight junction proteins in the colitis model was provided by a study by showing that administration of infliximab significantly improved the level of occludin but did not affect ZO-1 expression in DSS-induced colitis model." (PMID 37876728, 2023). "While there was no basic difference regarding the expression of ZO-1 and occludin in the untreated β6-KO and WT mice, loss of integrin β6 could rescue the depressed expression of ZO-1 and occludin in DSS-induced colitis." (PMID 37223685, 2023). "In the current work, the use of QT-NPs after induction of colitis played a significant role in the regulation of gene expression related to tight-junction proteins including occludin, MUC-2 and JAM, unlike the DSS-induced colitic non-treated group, which exhibited downregulation of those genes." (PMID 35884960, 2022). "The mRNA levels of Occludin, ZO-1 and claudin-1 were also upregulated in the 100 mg/kg of MR2938 group compared with the colitis group, though there was no statistical difference between the two groups." (PMID 41322271, 2025). "In IR62 treatment group, the all selected taxa, but not Muribaculum, exhibited a high correlation with all colitis-related markers except for TNF-α, IL-1β, iNOS, and occludin." (PMID 39849930, 2024). "Unlike ZO-1 and occludin, the expression of claudin 1 and claudin 2 was significantly upregulated in the majority of DSS-induced colitis mice when compared to the CTRL group without DSS treatment." (PMID 34395495, 2021). "Another research group found that the expression of both OCLN and CLDN3 is reduced and that CLDN1 is not affected in DSS-induced colitis compared to the control group." (PMID 32370215, 2020). "The mRNA expression levels of ZO-1 (P<0.001) and claudin-5 (P<0.01), but not occludin (P=0.587), were significantly higher in colonic tissues of HnAb-treated DSS-induced colitis mice than IgY-treated DSS-induced colitis mice." (PMID 33193406, 2020).
Stroke (77 papers, 2011 to 2025). Sudden impairment of blood flow to a part of the brain due to occlusion or rupture of an artery to the brain. "According to the results of the grid test and cylinder test, neurological function in occludin-deficient mice was significantly worse than that of wild-type mice from the early phase to the chronic phase after stroke." (PMID 36806348, 2023). "Previous study shows ischemic stroke causes reduction of occludin, claudin-1, and ZO-1 of the blood-brain barrier at 14 days post-stroke." (PMID 38107410, 2023). "It is possible that the more severe BBB dysfunction in occludin-deficient mice after stroke is due to the lower expression levels of claudin-5 and ZO-1 in the brain endothelial cells." (PMID 36806348, 2023). "The infarct volume in occludin-deficient mice 48 h after stroke was significantly larger than that in wild-type mice." (PMID 36806348, 2023). "The number of Ki-67 and LEL double-positive cells was significantly lower after stroke in occludin-deficient mice than in wild-type mice." (PMID 36806348, 2023). "This study aimed to investigate the dynamics and function of occludin across the acute and chronic phases after stroke using occludin-deficient mice." (PMID 36806348, 2023). "BBB integrity evaluated by Evans blue and 0.5-kDa fluorescein in the acute phase and by 10-kDa fluorescein isothiocyanate-labeled dextran in the chronic phase was decreased to a greater extent after stroke in occludin-deficient mice." (PMID 36806348, 2023). "The overall increase in BBB permeability after a stroke is closely linked to the decreased expression of tight junction proteins, such as claudin-5, occludin and ZO-1, among others." (PMID 34857032, 2021). "In this study, we found that the indicator of BBB damage (serum occludin) and stroke severity (baseline NIHSS score) were independent risk factors of HT using multivariate regression analysis." (PMID 34475814, 2021). "The most important result of the study was the finding that concentrations of occludin and claudin are associated with the type of stroke and stroke location." (PMID 33182224, 2020). "The location of stroke in the anterior part of the brain blood supply is associated with high blood levels of occludin and claudin 5 in the acute phase of stroke." (PMID 33182224, 2020). "For example, stroke is associated with decreased expression of the TJ proteins claudin-5, occludin, and ZO-1, among others." (PMID 33424628, 2020). "In line with the BBB permeability data, stroke-induced loss of tight junction proteins including ZO-1 and occludin was significantly attenuated by CAY10404 treatment in the ischemic brain, which were associated with significant reduction of MMP-9 activity." (PMID 32973660, 2020). "In contrast, another study demonstrated markedly elevated serum occludin concentrations in patients with moderate-to-severe cerebral infarction relative to those with milder strokes, and higher occludin levels were associated with poor outcomes in individuals who did not undergo reperfusion therapy." (PMID 41408503, 2025). "The decline in occludin levels post-stroke could pose a risk to blood–brain barrier (BBB) integrity, potentially worsening brain damage." (PMID 39309404, 2024). "In the present study, it was unclear whether occludin deficiency directly induced BBB dysfunction after stroke." (PMID 36806348, 2023). "In addition, recent studies reported some novel prognostic biomarkers associated with stroke outcomes, such as the middle cerebral artery pulsatility index, serum occludin levels, direct bilirubin, and stress‐induced hyperglycemia." (PMID 36415111, 2023). "Furthermore, occludin-deficient mice showed decreased claudin-5 and neovascularization after stroke." (PMID 36806348, 2023). "Furthermore, to determine the BBB integrity of occludin-deficient mice after stroke, extravascular leakage of Evans blue dye was evaluated 24 h after stroke, showing greater leakage in occludin-deficient than in wild-type mice." (PMID 36806348, 2023).
Stroke (continued). "We hypothesize that the combination of serum occludin level with other HT risk factors may further improve the predictive ability for HT in stroke patients with reperfusion therapy." (PMID 34475814, 2021). "Our findings are in line with the involvement of vitamin D on tight junction proteins in the blood-brain barrier, where vitamin D deficiency decreased the expression of occludin and claudin-5 and is suggested to complicate stroke severity and chronic consequences in rat." (PMID 31930458, 2020). "Similarly, stroke-induced loss of ZO-1 and occludin was significantly attenuated by CAY10404 treatment." (PMID 32973660, 2020). "In the cortex, we found a non-significant trend toward ZO-1 preservation with EP4 receptor activation, and significant preservation of dimeric occludin (125 kDa) in the ipsilateral cortex which was associated with reduced stroke-induced 65-kDa occludin, a likely phosphorylated form of occludin." (PMID 29527151, 2018). "Moreover, occludin-deficient mice had a higher post-stroke mortality rate than did wild-type mice." (PMID 36806348, 2023). "Therefore, the molecular mechanism underlying BBB deficiency after stroke in occludin-deficient mice remains unclear, and further studies are needed." (PMID 36806348, 2023). "Association between serum NLRP3 inflammasome and occludin levels with gender, infarction volume, TOAST subtypes and stroke severity." (PMID 41408503, 2025). "Conversely, the lowest levels of NLRP3 inflammasome and occludin were more commonly found in patients with small artery occlusion and other types of stroke." (PMID 41408503, 2025). "Among these, tight junction-associated proteins such as occludin, claudin-5 and ZO-1, which are essential for BBB integrity, have been explored as potential predictors of stroke severity and outcomes." (PMID 41408503, 2025). "We found that the structure of intestinal barrier integrity was badly damaged in aged-FTG mice on post-stroke day 3, with Claudin-1 and Occludin barely visible in immunofluorescence (IF) images." (PMID 39371609, 2024). "Second, in the present study we measured the association of serum occludin levels and PHE volumes within 24 h since stroke onset." (PMID 37721332, 2024). "For instance, upregulation of αvβ3 levels post-stroke induces the internalization of important tight junction proteins occludin and zonula occludens (ZO-1) in ECs and promotes the secretion of MMP-2 and MMP-9." (PMID 39000490, 2024). "Authors such as Zhang Y, Ji X, Li W, Wang Z, Wang Y, Li Y, Li X, Liu KJ, Zhang X, and Liu X are shown contributing to research areas including the BBB, ischemic stroke, occludin, stroke, tight junction proteins, inflammation, tight junctions, and ischemia." (PMID 39119484, 2024). "Herein, we have demonstrated that a biomarker panel of TJ proteins (OCLN, Claudin-5, and ZO-1) combined with a stroke severity scale, NIHSS, can be a good prediction model to differentiate between IS patients and SMs." (PMID 39595521, 2024). "This study aimed to conduct a comprehensive examination of the role of occludin in stroke pathogenesis spanning the years 2000–2023." (PMID 39119484, 2024). "Following a stroke, both groups experienced alterations in occludin expression, with a more pronounced effect observed in rats with pregnancies at an older age." (PMID 39309404, 2024). "Mounting evidence signifies that BBB disruption correlates with occludin and claudin-5 degradation in brain tissue, as well as the presence of occludin in the bloodstream following a stroke episode." (PMID 39119484, 2024). "By synthesizing existing literature and exploring the scientific landscape surrounding occludin in the context of stroke, we seek to contribute valuable insights into the molecular mechanisms underpinning BBB dysfunction and the development of ischemic stroke." (PMID 39119484, 2024).
Stroke (continued). "Previous research has shown that the BBB is disrupted during a stroke, resulting in alterations in the concentrations and distributions of Claudin-5, OCLN, ZO-1, and other BBB building blocks." (PMID 39595521, 2024). "Collectively, these findings support the idea that occludin deficiency causes increased infarct volume and BBB dysfunction, as well as deteriorated neurological function after photothrombotic stroke in mice." (PMID 36806348, 2023). "Occludin and claudin-5 mRNA decreased rapidly 3 h after stroke onset, while ZO-1 mRNA decreased gradually." (PMID 36806348, 2023). "In rodent models of stroke and traumatic brain injury, claudin-5, occludin, and ZO-1 were down-regulated with the opening of the BBB leading to extravasation of serum proteins." (PMID 37185751, 2023). "At 24 h after stroke, the expression level of occludin was decreased in the brain endothelial cells of ischemic lesions." (PMID 36806348, 2023). "Next, as occludin is a critical molecule for preserving the BBB permeability, we demonstrated that the perioperative stroke mice exhibited more severe occludin loss in the ischemic penumbra when assayed at 3 days following tMCAO (P < 0.0001)." (PMID 35799259, 2022). "In stroke patients, Eda.B reduced the serum levels of NETs and occludin, and occludin level was positively correlated with NETs." (PMID 36032782, 2022). "Lentiviral mediated overexpression in ischemic brains significantly attenuated the decrease of tight junction proteins ZO-1 and occludin, and reduced IgG leakage to the brain tissue three days after stroke." (PMID 35346266, 2022). "Our result showed that serum occludin increased in AIS patients, and stroke decreased the level of TJ-associated proteins in perivascular space of mouse cortex." (PMID 36032782, 2022). "A second study has demonstrated the role of occludin phosphorylation at S490 as a major regulator of tissue plasminogen activator (tPA)-induced BBB permeability in the context of stroke." (PMID 36320068, 2022). "Serum occludin levels after thrombectomy were found to be significantly correlated with the NIHSS score within 24 h of a stroke (r = 0.52, p < 0.001)." (PMID 35338575, 2022). "Numerous reports in a variety of models (e.g., SCI, stroke, MS) suggest that imatinib alters endothelial tight junction protein expression (e.g., claudin 5, occludin, e-cadherin, connexin 43, beta-catenin) and improves vascular integrity." (PMID 35528149, 2022). "As a component of the blood–brain barrier tight junction protein, serum occludin is also considered one of the biomarkers to predict the prognosis of stroke." (PMID 35789538, 2022). "We confirmed that high serum occludin levels were closely related to END for stroke patients with successful EVT." (PMID 35338575, 2022). "The mRNA expressions of TJ proteins (ZO-1, occludin, and claudin-1) in mice decreased significantly in the stroke 1-day group (n = 5, p < 0.001), but the difference had not reached significance after 7 days of stroke (n = 5, p > 0.05)." (PMID 33642941, 2021). "Our previous studies have suggested that serum occludin levels can reflect the destruction of the BBB after stroke and act as a specific marker of BBB injury." (PMID 33269096, 2020). "The results showed that baseline serum occludin levels were significantly elevated in the acute stroke group compared with the pseudo strokes group (4.24±1.37 ng/mL vs 2.36±0.96 ng/mL, P<0.001)." (PMID 33269096, 2020). "Considering that we measured the parameters before the end of the first day of stroke, the occurrence of occludin and claudin-5 was most probably due to ischemic reperfusion injury." (PMID 33182224, 2020). "The mean concentration of occludin in patients with location of stroke in the carotid artery supply was significantly more often than in the vertebrobasilar supply." (PMID 33182224, 2020). "Multiple logistic regression analysis was used to analyze the relationship between serum occludin and stroke prognosis." (PMID 33269096, 2020).
Stroke (continued). "To date, it has been established in animal and human studies that the levels of occludin and claudin change over time on the initial days following the onset of stroke." (PMID 33182224, 2020). "In all patients, the plasma concentrations of claudin-5, occludin, and ZO-1 on the first day of stroke were examined and next, the mean concentrations were analyzed and compared between subgroups created on the basis of demographical and clinical features." (PMID 33182224, 2020). "The expression of occludin in the endothelial cells of the brain capillaries is lowered during stroke." (PMID 33182224, 2020). "In fact, at early stage of AIS (<24 hours after stroke onset), serum occludin level reflects the severity of BBB damage, since degraded occludin is directly associated with BBB damage." (PMID 33269096, 2020). "Claudin and occludin occur in the blood of patients during the acute period of stroke as a result of the dysregulation of the blood–brain barrier." (PMID 33182224, 2020). "Based on the NIHSS score and occludin level on admission, the assessment of stroke prognosis will be more accurate and reliable, and it needs to be confirmed by further prospective cohort studies." (PMID 33269096, 2020). "In order to clarify the relationship between serum occludin and the ischemic duration, patients were classified into four groups according to time interval from the onset of stroke symptoms to the arrival of the hospital (0-6 h, 6-12 h, 12-24 h, >24 h)." (PMID 33269096, 2020). "By immunohistochemical staining (IHC), occludin signal was reduced at both time points within the stroke region in comparison to CD31 staining reaching significance on 7 days post-stroke." (PMID 32300291, 2020). "In stroke patients, the serum concentrations of occludin and claudin, the key structural components of the BBB, result from damage to the BBB." (PMID 33182224, 2020). "This study confirmed that serum occludin level in the acute stroke group was significantly higher than that of the pseudo stroke group, which reflected the close relationship between BBB injury and acute stroke." (PMID 33269096, 2020). "The ROC curve analysis showed that baseline serum occludin was significantly predictive of stroke occurrence, with an AUC value of 0.875 (95% confidence interval: 0.815-0.934, p<0.001), with a threshold of 2.61 ng/mL." (PMID 33269096, 2020). "Serum occludin levels were significantly elevated in acute stroke cases compared with those with stroke-like symptoms (P<0.001)." (PMID 33269096, 2020). "The confocal microscopy images showed that NBP treatment significantly attenuated ZO-1 and occludin-mediated gap formation in the microvessel wall induced by stroke, thereby preserving tight junction protein structural integrity at 1 and 3 days after tMCAO." (PMID 33510620, 2020). "In our study, the concentrations of claudin 5 and occludin were higher in patients whose stroke was located in the area of carotid artery vascular supply, as compared with those whose stroke was located in the area supplying the basilar artery." (PMID 33182224, 2020). "We show that RA associates to worse stroke-outcome via exacerbated BBB degradation by decrease of the TJPs claudin-5 and occludin." (PMID 30778120, 2019). "The tPA-DHI combination significantly reduced degradation of claudin-5, occludin and ZO-1 at 24 h after stroke." (PMID 29681849, 2018). "The expression of the tight junction proteins claudin-5 and occludin were measured by Western blot in isolated microvessels from brains of control and obese ob/ob mice at 4 or 24 h post-stroke." (PMID 26823471, 2017). "MMP-2/9 has been shown to mediate BBB disruption by degrading TJ proteins such as occludin and claudin-5 in an animal stroke model and an in vitro ischemic model." (PMID 25815722, 2015). "Chinese researchers have made important advances in our understanding of occludin in stroke." (PMID 39119484, 2024).